CKB (creatine kinase B)
Description:
Reversibly catalyzes the transfer of phosphate between ATP and various phosphogens (e.g. creatine phosphate). Creatine kinase isoenzymes play a central role in energy transduction in tissues with large, fluctuating energy demands, such as skeletal muscle, heart, brain and spermatozoa (Probable). Acts as a key regulator of adaptive thermogenesis as part of the futile creatine cycle: localizes to the mitochondria of thermogenic fat cells and acts by mediating phosphorylation of creatine to initiate a futile cycle of creatine phosphorylation and dephosphorylation (By similarity). During the futile creatine cycle, creatine and N-phosphocreatine are in a futile cycle, which dissipates the high energy charge of N-phosphocreatine as heat without performing any mechanical or chemical work (By similarity).
Synonyms: B-CK; CPK-B; CKBB; BCK; HEL-211; HEL-S-29
Tractability: Small molecule: a structure with a bound ligand is known; it has a high-quality binding pocket. Antibody: UniProt places it where antibodies can reach, with high confidence; its Gene Ontology location is reachable by antibodies, with medium confidence. PROTAC: UniProt records ubiquitination sites on it; ubiquitination databases record sites on it; its protein half-life has been measured.
Target class: Enzyme; Transferase
Gene: Protein-coding gene on chromosome 14 (103,519,660 to 103,523,167, reverse strand). Ensembl gene ENSG00000166165.
Subcellular location: Cytoplasm, cytosol; Mitochondrion; Cell membrane
Subcellular location (Human Protein Atlas): Cytosol
Pathways (Reactome):
Metabolism: Creatine metabolism
Signal Transduction: RND3 GTPase cycle
Gene Ontology:
Molecular function: creatine kinase activity; protein binding; ubiquitin protein ligase binding; catalytic activity; kinase activity; phosphotransferase activity, nitrogenous group as acceptor; transferase activity, transferring phosphorus-containing groups
Biological process: phosphocreatine biosynthetic process; substantia nigra development; futile creatine cycle
Cellular component: cytosol; extracellular exosome; plasma membrane; extracellular region; mitochondrion
Genetic constraint (gnomAD): Loss-of-function variants: 12 observed, 26.84 expected, observed/expected ratio (o/e) 0.45, 90% interval 0.28 to 0.72. The upper end of that interval is the gene's LOEUF score, 0.72, which puts it in group 2 of 6, group 1 being the genes least tolerant of losing a copy. Missense variants: 394 observed, 447.58 expected, observed/expected ratio (o/e) 0.88, 90% interval 0.81 to 0.96. Synonymous variants: 238 observed, 199.14 expected, observed/expected ratio (o/e) 1.2, 90% interval 1.07 to 1.33.
Homologues: Orthologues: chimpanzee CKB (100% identical), dog CKB (98% identical), pig CKB (97% identical), rabbit CKB (97% identical), guinea pig CKB (97% identical), mouse Ckb (97% identical), zebrafish ckbb (86% identical), rat Ckb (85% identical), zebrafish ckba (84% identical), tropical clawed frog ckb (82% identical), macaque CKB (66% identical), Drosophila melanogaster Argk1 (41% identical), and 8 more. Paralogues in human: CKM (81% identical), CKMT1A (67% identical), CKMT1B (67% identical), CKMT2 (64% identical).
Diseases named in the same sentence as CKB in open-access papers:
CKB is named in the same sentence as 98 diseases in open-access papers, as found by Europe PMC text mining. Sharing a sentence is not in itself a finding about the gene and the disease. The quoted sentences say what the papers report.
ovarian carcinoma (11 papers, 2004 to 2025). A malignant neoplasm originating from the surface ovarian epithelium. "With regard to CTNNBL1, UQCC1 and CKB, all of them have been previously associated to ovarian cancer." (PMID 35120576, 2022). "An increase in p21 and a reduced proliferation rate have also been previously reported after CKB siRNA transfection in ovarian cancer cells." (PMID 41345636, 2025). "Mechanistic studies have suggested that CKB is involved in the regulation of energy homeostasis and metabolic state in ovarian cancer." (PMID 35120576, 2022). "Another study reported that the CKB expression level is increased in some ovarian cancer tissues, and the knockdown of CKB can delay disease progression by decreasing glycolysis." (PMID 35664305, 2022). "CKB is highly expressed in early stage ovarian tumour tissues and is, therefore, a potential biomarker for the early detection of ovarian cancer; it should be further investigated." (PMID 33800113, 2021). "In many ovarian cancer cells a CKB over-expression was detected, suggesting an important role in cancer progression." (PMID 28724347, 2017). "It was found that knockdown of CKB cells decreased glycolysis in ovarian cancer." (PMID 35712500, 2022). "Finally, CKB gene expression has been reported to be up-regulated in ovarian cancer cells in vitro and in vivo and CKB enzyme activity to be significantly elevated in sera from ovarian cancer patients, including those with stage I disease." (PMID 35120576, 2022). "It has been reported that certain ovarian cancer tissues have improved protein CKB expression." (PMID 33800113, 2021). "Gene array technology has recently identified prostasin (a serine protease, previously identified in prostatic secretions), osteopontin (a secreted bone morphogen) and creatine kinase B (a marker for renal and lung cancers) to be elevated in serum from patients with ovarian cancer." (PMID 15199385, 2004). "Additionally, we identified some candidate genes linked to reproductive diseases, such as NRG3 and XRCC3 for ovarian cancer, and BAG5, CKB and XRCC3 for endometriosis." (PMID 33477586, 2021).
colon cancer (10 papers, 2014 to 2025). "Since a controversial role of CKB has been reported in colon cancer [20−22], we examined the association of CKB expression with colon cancer prognosis in its TCGA dataset (N = 640, access via cBioportal)." (PMID 34706306, 2021). "Consistently, in colon cancer, extracellular CKB sustains cell survival in hypoxic conditions during transit to metastatic sites in the liver." (PMID 41072771, 2025). "CKB also colocalizes with E-cadherin in colon cancer cells and is important for the assembly of the adherens junction and the maintenance of epithelial integrity." (PMID 41345636, 2025). "A study on colon cancer cell line SW480 demonstrated that overexpression of CKB increased intracellular PCr levels." (PMID 35712500, 2022). "CKB has been shown to be downregulated by miRNAs in colon cancer or by promoter methylation in gastric cancer." (PMID 34706306, 2021). "Two more recent studies drawn different conclusions in CKB's role in liver metastasis of colon cancer cells, both starting with CKB being a target of some miRNAs in colon cancer cells." (PMID 34706306, 2021). "The bottom 15% of TCGA colon cancer tumors with the lowest CKB expression have significantly shorter overall survival as compared to all other cases (P = 0.025)." (PMID 34706306, 2021). "CKB has been reported to contribute to colon cancer progression and liver metastasis, with discrepancies in different studies." (PMID 34706306, 2021). "These authors showed that the overexpression of CKB-C283S, a dominant-negative construct with effects similar to CKB downregulation, appears to promote the epithelial-to-mesenchymal transition in colon cancer." (PMID 26460485, 2015). "Of all those genes, down-regulation of CKB gene was reported to promote epithelial-to-mesenchymal transition (EMT) in colon cancer." (PMID 24884630, 2014). "CKB's role in cancer types other than colon cancer is largely unknown, especially in those cancers where liver is not the dominant metastatic site, such as prostate cancer." (PMID 34706306, 2021). "Moreover, overexpression of dominant negative CKB mutants was found to promote an epithelial-to-mesenchymal transition (EMT) in colon cancer cells." (PMID 27527620, 2016). "The attenuated expression of CK enzymes in IBD tissue suggests that intestinal Cr metabolism and PCr/CK energetics may be compromised in at least a subset of IBD patients, and several studies have identified reduced levels of CKB in colonic tumors." (PMID 27527620, 2016). "Since colon cancer-derived liver metastases carry higher creatine kinase brain type (CKB) levels compared to primary tumors, UBC metastatic populations, in order to overcome hypoxia and other metabolic stresses, may also upregulate CKB expression or/and activity." (PMID 32164285, 2020). "In addition, the authors showed that although CKB expression may be advantageous to the formation of a solid tumor, it appears to be a hindrance to the metastatic potential of colon cancer cells." (PMID 26460485, 2015). "The downregulation of CKB promotes EMT and accelerate colon cancer progression." (PMID 31737124, 2019).
Obesity (9 papers, 2021 to 2024). Accumulation of substantial excess body fat. "In summary, these data provide further evidence that CKB and CCL2 dysregulation in obesity is linked to increased CpG methylation of the proximal promoter region of CKB." (PMID 39675471, 2024). "Brown adipocyte-specific CKB knockout mice showed reduced mitochondrial respiration in primary brown adipocytes and increased susceptibility to diet-induced obesity." (PMID 39107469, 2024). "•In obesity, CKB promoter methylation associates with CKB gene expression and adipose inflammation." (PMID 39675471, 2024). "Overall, our study uncovers a regulatory axis where ER stress drives inflammation in obesity by reducing CKB abundance, and consequently altering the bioenergetic state of the cell." (PMID 39675471, 2024). "By screening conditions perturbed in obesity, we identified endoplasmic reticulum (ER) stress as a key suppressor of CKB transcription across multiple cell types." (PMID 39675471, 2024). "In white adipose tissue, disturbed creatine metabolism through reduced creatine kinase B (CKB) transcription contributes to obesity-related inflammation." (PMID 39675471, 2024). "In this regard, recent studies in obesity reported that inactivation of CKB in adipocytes decrease thermogenic capacity, highlighting the important role of BAT in energy expenditure by generating heat through this process." (PMID 38703299, 2024). "On the other hand, it has been studied the increase of creatine kinase B (CKB), known to promote thermogenesis, has been investigated as a potential approach to counteract obesity." (PMID 38703299, 2024). "We validated our findings in vivo, demonstrating that individuals living with obesity show an inverse relationship between CKB expression and promoter methylation in white adipocytes, along with elevated CCL2 secretion." (PMID 39675471, 2024). "Transgenic mice depleted of CKB, CKMT1B, and GATM showed impaired creatine biosynthesis capacity affecting the murine body weight and resulting in a susceptibility to obesity." (PMID 37101650, 2023). "The CDSs of CKB, CKMT1B, and GATM were subsequently screened for variants in 192 children and adolescents with severe obesity as well as 192 healthy-lean controls." (PMID 37101650, 2023). "Moreover, the single nucleotide polymorphisms in CKB and CKMT1B were associated with BMI54, indicating that CKB and CKMT1 are involved in the pathogenesis of obesity in vivo." (PMID 39107469, 2024). "More importantly, we also observed that freshly isolated fat cells from people living with obesity recapitulate our in vitro observations as they display ER stress, lower CKB expression, increased methylation of the CKB promoter and higher levels of CCL2 compared to non-obese individuals." (PMID 39675471, 2024). "While phosphocreatine metabolism is impaired in obesity, adipocyte deletion of creatine kinase B increases the ATP:ADP ratio in adipocytes and promotes a pro-inflammatory state within adipose tissue, demonstrating the role of creatine kinase B as a mediator of pathophysiological adipose remodelling." (PMID 38755301, 2024). "The presence of infrequent non-synonymous variants in CKB and CKMT1B (rs146047573, rs758572075, rs1230355611, and rs149544188) was confirmed in independent study groups comprising 781 families with severe obesity, 320 children and adolescents with severe obesity, and 253 healthy lean controls." (PMID 37101650, 2023). "Metabolic comparisons of metformin and selective AMPK activation, as well as CKB induction in experimental in vivo models of obesity may address this relationship." (PMID 35165448, 2022). "With this, the infrequent alleles of the variants rs76220640 (p.Pro112 =) and rs146047573 (p.Tyr269Cys) located in CKB, the CKMT1B variant rs9571's allele (p.Lys352 =) as well as the allele of the GATM-located variant rs747005297 (p.His292Arg) were nominally associated with obesity." (PMID 37101650, 2023).
Obesity (continued). "Decreased levels of CKB abundance were found on SAT and VAT of individuals with obesity compared to lean subjects." (PMID 38703299, 2024). "In the individuals with obesity, we found higher abundance of both XBP1 expression and splicing, and the total levels correlated negatively with CKB (rho = −0.5129; P = 0.0027), also after correction for BMI in a multiple regression analysis." (PMID 39675471, 2024). "For CKB, CKMT1B and GATM, subsequent analyses revealed gene expression differences between VAT and SAT in 1,448 adipose tissue donors with obesity." (PMID 37101650, 2023). "Second, we investigated the relationship between XBP1 splicing and CKB expression in white adipose tissue samples from a cohort of people living with and without obesity." (PMID 39675471, 2024). "Together with the observation that re-expression of CKB attenuates CCL2 production, our data in vitro and in vivo suggest that restoration of creatine metabolism might mitigate tissue inflammation in obesity and insulin resistance." (PMID 39675471, 2024). "Thus, the VAT of participants with and without obesity showed a higher expression of CKB than the SAT of patients with obesity." (PMID 37101650, 2023). "By analyzing RNA-seq data of VAT and SAT of 1,479 individuals (1,448 with obesity and 31 non-obese) of the Leipzig Obesity Biobank, we detected that all three genes of interest (CKB, CKMT1B and GATM) showed positive correlations with each other in visceral fat." (PMID 37101650, 2023). "Based on these data, we analyzed correlations between CKB, CKMT1B, and GATM expression levels and specific metabolic and anthropometric parameters in both VAT and SAT of participants with and without obesity." (PMID 37101650, 2023). "Considering the inverse correlations of CKB with CKMT1B and GATM in visceral and subcutaneous adipose tissue, we subsequently performed between-subject comparisons of non-obese participants and individuals with obesity from the LOBB for all three genes studied." (PMID 37101650, 2023).
colorectal cancer (6 papers, 2018 to 2023). A primary or metastatic malignant neoplasm that affects the colon or rectum. "The Human Protein Atlas shows that colorectal cancer is a cancer with high expression of both CKB and MTCK." (PMID 37204253, 2023). "Gastrin-release Pepper (GRP) and its receptor (GRPR) are abnormally highly expressed in colorectal cancer, while CKB is significantly higher in cell lines expressing GRP/GRPR." (PMID 34354842, 2021). "Colorectal cancer liver metastases have been shown to secrete creatine kinase brain-type (CKB) into the ECM." (PMID 31668988, 2020). "CKB is one of the mechanisms of intrahepatic metastasis of colorectal cancer." (PMID 34354842, 2021). "In another study, Torres and colleagues demonstrated that CKB is 1 of the 2 shared targets of 3 metastasis-promoting miRNAs (miR-424-3p, -503, and -1292), and CKB downregulation increased cell adhesion and proliferation in colorectal cancer cells, as well as their seeding in liver in vivo." (PMID 34706306, 2021). "Here, we analyzed the expression and function of CKB and MTCK in colorectal cancer (CRC) and investigated the role of the creatine shuttle in CRC." (PMID 37204253, 2023).
hepatocellular carcinoma (6 papers, 2012 to 2025). A malignant tumor that arises from hepatocytes. "Our findings complement prior work that has demonstrated a role for CKB in promoting cell survival, migration, chemotaxis, and metastasis in hepatocellular carcinoma, pancreatic ductal adenocarcinoma, prostate cancer, osteosarcoma, and estrogen receptor–negative breast cancer." (PMID 41072771, 2025). "Moreover, AKT was recently shown to inhibit GPX4 degradation through creatine kinase B-dependent phosphorylation, thereby mitigating ferroptosis in hepatocellular carcinoma cell lines." (PMID 38097548, 2023). "Notably, the levels of CKB T133 and GPX4 S104 phosphorylation have been associated with poor prognosis of patients with hepatocellular carcinoma, thus linking ferroptosis evasion to the non-metabolic moonlighting function of CKB." (PMID 38908072, 2024). "The interaction between creatine kinase B (CKB) and GPX4 facilitated the phosphorylation of GPX4 at S104, mitigated autophagic degradation of GPX4, and suppressed ferroptosis in hepatocellular carcinoma." (PMID 38844964, 2024). "The results were further validated by RT-PCR, western blot, flow cytometry or immunofluorescent staining which revealed that prominin-1, annexin A1, annexin A3, transgelin, creatine kinase B, vimentin, and EpCAM were indeed highly expressed in the CD133-positive hepatoma cells." (PMID 23170877, 2012).
Huntington disease (6 papers, 2013 to 2024). Huntington disease (HD) is a rare neurodegenerative disorder of the central nervous system characterized by unwanted choreatic movements, behavioral and psychiatric disturbances and dementia. "Reduced CKB activity is associated with hearing impairment in mice with Huntington disease." (PMID 38846638, 2024). "Enhancement of CKB activity was able to rescue ATP depletion, aggregate formation and impaired proteasome activity in a Huntington's disease mouse model." (PMID 24278208, 2013). "Furthermore, CKB is decreased in the brains of patients with neurodegenerative disorders including Alzheimer disease, Huntington disease, and Pick disease." (PMID 23805272, 2013).
Stroke (5 papers, 2018 to 2024). Sudden impairment of blood flow to a part of the brain due to occlusion or rupture of an artery to the brain. "Further exploration of these candidates in human plasma revealed the potential of CKB and CMPK to diagnose stroke, while CaMK2B and CMPK resulted feasible biomarkers of functional stroke outcome." (PMID 29784938, 2018). "We further aimed to assess the potential role of CKB, CaMK2B, CaMK2D, CaMK2A and CMPK as biomarkers of stroke." (PMID 29784938, 2018).
Insulin resistance (4 papers, 2022 to 2024). Increased resistance towards insulin, that is, diminished effectiveness of insulin in reducing blood glucose levels. "Second, insulin resistance, as a criterion of MAFLD diagnosis, was not assessed in our study due to the lack of serum insulin data in CKB." (PMID 36035906, 2022).
pancreatic cancer (4 papers, 2021 to 2024). "Of note, in 6 of the 7 cancer types, tumors with lower CKB associate with significantly shorter overall patient survival, including cervical, head-neck, kidney, ovarian, pancreatic cancer and sarcoma." (PMID 34706306, 2021). "For example, a recent study found that low serum levels of CKB predict poor survival in pancreatic cancer." (PMID 39769038, 2024). "The creatine kinase B (CKB)-dependent creatine-phosphagen system was reported to facilitate the invasiveness of pancreatic cancer cells." (PMID 37370109, 2023). "In pancreatic cancer, the enzyme creatine kinase B (CKB) is gradually up-regulated with stiffening substrates in a YAP-dependent manner, which is thought to provide the ATP needed for a faster actin turnover at the cell's leading front." (PMID 37610008, 2023). "In another recent study, authors found that matrix stiffness controlled the expression of CKB, and a stiffer matrix could induce creatine metabolism and enhance metastasis of pancreatic tumors through the activation of YAP signaling." (PMID 39769038, 2024).